SMIM44 (small integral membrane protein 44)
Synonyms: CTF5; NFI1_HUMAN; NFI2_HUMAN
Gene: Protein-coding gene on chromosome 19 (3,482,110 to 3,483,441, reverse strand). Ensembl gene ENSG00000284638.
Subcellular location: Membrane
Gene Ontology:
Cellular component: membrane
Homologues: Orthologues: chimpanzee SMIM44 (99% identical), macaque SMIM44 (95% identical), pig SMIM44 (81% identical), rat Smim44 (69% identical), mouse Gm48552 (68% identical).